ETNPPL (ethanolamine-phosphate phospho-lyase)
Description:
Catalyzes the pyridoxal-phosphate-dependent breakdown of phosphoethanolamine, converting it to ammonia, inorganic phosphate and acetaldehyde.
Synonyms: AGXT2L1
Tractability: Small molecule: it belongs to a druggable protein family.
Gene: Protein-coding gene on chromosome 4 (108,741,969 to 108,763,228, reverse strand). Ensembl gene ENSG00000164089.
Subcellular location: Mitochondrion
Subcellular location (Human Protein Atlas): Nucleoplasm
Pathways (Reactome):
Metabolism: Synthesis of PE
Gene Ontology:
Molecular function: ethanolamine-phosphate phospho-lyase activity; protein binding; pyridoxal phosphate binding
Cellular component: mitochondrial matrix; mitochondrion
Genetic constraint (gnomAD): Loss-of-function variants: 10 observed, 26.04 expected, observed/expected ratio (o/e) 0.38, 90% interval 0.24 to 0.65. The upper end of that interval is the gene's LOEUF score, 0.65, which puts it in group 2 of 6, group 1 being the genes least tolerant of losing a copy. Missense variants: 304 observed, 380.83 expected, observed/expected ratio (o/e) 0.8, 90% interval 0.73 to 0.88. Synonymous variants: 118 observed, 132.42 expected, observed/expected ratio (o/e) 0.89, 90% interval 0.77 to 1.04.
Homologues: Orthologues: chimpanzee ETNPPL (99% identical), macaque ETNPPL (94% identical), dog ETNPPL (90% identical), pig ETNPPL (89% identical), mouse Etnppl (84% identical), rabbit ETNPPL (84% identical), rat Etnppl (83% identical), guinea pig ETNPPL (75% identical), tropical clawed frog etnppl (74% identical), zebrafish etnppl (64% identical). Paralogues in human: PHYKPL (58% identical), AGXT2 (33% identical), OAT (21% identical), ABAT (21% identical).
Diseases named in the same sentence as ETNPPL in open-access papers:
ETNPPL is named in the same sentence as 35 diseases in open-access papers, as found by Europe PMC text mining. Sharing a sentence is not in itself a finding about the gene and the disease. The quoted sentences say what the papers report.
glioma (13 papers, 2020 to 2025). A benign or malignant brain and spinal cord tumor that arises from glial cells (astrocytes, oligodendrocytes, ependymal cells). "While nuclear localization of ETNPPL has been observed in gliomas and glioblastomas—particularly when over-expressed this does not correlate with the SNc neurons of either PD patients or controls." (PMID 39684817, 2024). "The expression level of ETNPPL negatively correlates with the progression of some gliomas, suggesting the potential of Etnppl as a glioma marker." (PMID 36794261, 2023). "Overexpression of ETNPPL in a glioma reduces its proliferation, suggesting that ETNPPL regulates glioma proliferation." (PMID 36794261, 2023). "Some studies have shown that ETNPPL plays a certain role in glioma, gastric cancer, and liver fibrosis." (PMID 36295481, 2022). "Overexpression of ETNPPL protein can exhibit tumor suppressive effect and inhibit the proliferation of glioma stem cells." (PMID 36040678, 2022). "Overexpression of ETNPPL reduced the growth of glioma stem cells and ETNPPL expression was inversely correlated to glioma grade." (PMID 34549263, 2021). "This is consistent with glioma database analyses showing that ETNPPL expression is inversely correlated to STAT3 and MKI67 whose expression are higher in foci and glioblastomas." (PMID 32218467, 2020). "Overexpression of ETNPPL reduces the growth of glioma stem cells indicating that this enzyme opposes gliomagenesis." (PMID 32218467, 2020). "We demonstrated that the ETNPPL protein is present in normal astrocytes as well as in diffuse low-grade glioma cells but is downregulated with malignant progression." (PMID 32218467, 2020). "ETNPPL protein overexpression reduces glioma stem cell growth." (PMID 36776000, 2023). "Furthermore, ETNPPL protein has been found to have decreased expression in human glioma brain tumors, which further decreases with malignant progression." (PMID 34048714, 2021). "We detected ETNPPL protein in glioma cells as well as in astrocytes in the human brain." (PMID 32218467, 2020). "In addition, this led us to identify expression of ETNPPL in gliomas, a barely-studied metabolic enzyme, which was further studied in vitro." (PMID 32218467, 2020). "We also examined the ETNPPL expression in gliomas cells using DLGG primary cultures." (PMID 32218467, 2020). "We then analyzed ETNPPL expression in diffuse low-grade gliomas samples." (PMID 32218467, 2020). "This prompted us to explore the expression and role of ETNPPL in the human brain and gliomas." (PMID 32218467, 2020). "Therefore, the high expression of ETNPPL in low-grade gliomas and its under-expression in high-grade gliomas may indicate that reduced phosphoethanolamine and phosphatidylethanolamine synthesis might inhibit glioma cell growth." (PMID 39684817, 2024). "We can thus speculate that the high expression of ETNPPL found in diffuse low-grade gliomas and its overexpression done here in glioblastoma cells may reduce phosphoethanolamine concentration and phosphatidylethanolamine synthesis causing reduction in glioma cell growth." (PMID 32218467, 2020). "On the other hand, ETNPPL, a gene inversely associated with DRAXIN, is also negatively associated with the grade of glioma as its expression is not detected in glioblastomas." (PMID 36040678, 2022). "ETNPPL expression is inversely correlated to glioma grade and we found no ETNPPL protein in glioblastomas." (PMID 32218467, 2020).
glioblastoma (5 papers, 2020 to 2024). The most malignant astrocytic tumor (WHO grade IV). "ETNPPL is underexpressed in primary glioblastoma (GBM) and shows potential diagnostic implication for GBM." (PMID 34549263, 2021). "We found that ETNPPL RNA and protein are reduced in foci cells and absent in glioblastomas." (PMID 32218467, 2020).
gastric cancer (3 papers, 2022 to 2023). A primary or metastatic malignant neoplasm involving the stomach. "Studies have shown that ETNPPL is downregulated in malignancies, including colorectal cancer, gastric cancer and pancreatic cancer, and low expression of ETNPPL indicates poorer prognosis." (PMID 37637156, 2023). "There was no statistical significance in six kinds of immune cell infiltration results of the ETNPPL gene in gastric cancer." (PMID 36140749, 2022). "Besides ETNPPL, the other four genes were also found to be closely related to the immune infiltration of gastric cancer, and the immune infiltration of five genes in other gastrointestinal cancers has a certain reference value for future studies." (PMID 36140749, 2022).
astrocytoma (2 papers, 2020 to 2024). "In contrast, another study observed ETNPPL protein in both the cytoplasm and nucleus of astrocytoma cells." (PMID 39684817, 2024). "By IHC and reminiscent of what was observed in the normal brain, ETNPPL was detected either in the cytoplasm or the nuclei of the cells in one grade II astrocytoma." (PMID 32218467, 2020).
brain tumors (2 papers, 2020 to 2021). "Little is known about ETNPPL (13 publications) and a potential link with brain tumours has not been established." (PMID 32218467, 2020).
atrial fibrillation (1 paper, 2022). A disorder characterized by an electrocardiographic finding of a supraventricular arrhythmia characterized by the replacement of consistent P waves by rapid oscillations or fibrillatory waves that vary in size, shape and timing and are accompanied by an irregular ventricular response. "In our present study, ETNPPL as a significantly down-regulated gene in patients with dilated cardiomyopathy-induced heart failure and atrial fibrillation was detected." (PMID 36295481, 2022). "Finally, five genes (FRZB, SFRP4, ETNPPL, AQP4, C1orf105) were found to be highly co-expressed in patients with heart failure and atrial fibrillation." (PMID 36295481, 2022).
Hyperinsulinemia (1 paper, 2025). An increased concentration of insulin in the blood. "The ETNPPL gene was recently implicated also in hyperinsulinemia-induced insulin resistance." (PMID 39746953, 2025).
Insulin resistance (1 paper, 2025). Increased resistance towards insulin, that is, diminished effectiveness of insulin in reducing blood glucose levels. "The metabolic enzyme ethanolamine-phosphate phosphorylase (ETNPPL) was found to inhibit autophagic flux-mediated PA-induced insulin resistance in hepatocytes via the ARG2/ROS signaling cascade, suggesting that targeting ETNPPL may be a potential approach for the treatment of T2DM." (PMID 40969373, 2025).
oligodendroglioma (1 paper, 2020). A well-differentiated (WHO grade II), diffusely infiltrating neuroglial tumor, typically located in the cerebral hemispheres. "In the oligodendroglioma, we found that >95% of ETNPPL+ cells also expressed the mutated form of IDH1 R132H." (PMID 32218467, 2020). "Either cytoplasmic or nuclear expression of ETNPPL was detected in tumoral cells identified by the expression of IDH1R132H in one oligodendroglioma." (PMID 32218467, 2020).
sarcopenia (1 paper, 2022). Progressive decline in muscle mass due to aging which results in decreased functional capacity of muscles. "In this study, seven genetic biomarkers closely associated with sarcopenia, such as CISD1, ETNPPL, and WISP2, were identified by RF and were used to construct a diagnostic prediction model for sarcopenia with high diagnostic performance." (PMID 36050999, 2022). "The proteins encoded by three of these genes (CISD1, ETNPPL, and WISP2) may be potential biomarkers for sarcopenia." (PMID 36050999, 2022). "Surprisingly, during the analysis to construct the diagnostic model of sarcopenia, three key genes (CISD1, ETNPPL, and WISP2) that might play a vital role in the pathogenesis were identified for the first time." (PMID 36050999, 2022). "In this study, the expression of ETNPPL was significantly lower in sarcopenia samples than in normal samples, which indirectly supported our hypothesis." (PMID 36050999, 2022).
tumor (4 papers, 2020 to 2023). "Moreover, low levels of ETNPPL were associated with advanced tumor node metastasis classification (TNM) stage, poor grade, and tumor metastasis." (PMID 37637156, 2023). "Over-expression of ETNPPL inhibited the migration and invasion of tumor cells, suggesting that ETNPPL plays a tumor suppressive role." (PMID 37637156, 2023). "Collectively, these data show that ETNPPL is expressed in diffuse low-grade tumours and is reduced with malignant progression." (PMID 32218467, 2020). "The expression of ETNPPL was significantly downregulated in HCC tissues, compared with paracarcinoma non-tumor tissues." (PMID 37637156, 2023). "Thus, in the absence of other discriminatory markers, overexpression of DDP10, ETNPPL and SH3GL2 in DA + AA vs GBM might be considered in distinguishing these tumor subgroups, particularly for unclassifiable tumors or in case of small biopsy samples." (PMID 32647207, 2020). "Therefore, we hypothesized that ETNPPL might be an important gene in the regulation of cellular phospholipid synthesis, and ETNPPL knockdown in tumor cells would lead to the accumulation of endogenous PEA, thereby acting as a tumor suppressor." (PMID 37637156, 2023).
cancer (3 papers, 2020 to 2023). A tumor composed of atypical neoplastic, often pleomorphic cells that invade other tissues. "Expression of 2 genes coding for metabolic enzymes (ALDOC, ETNPPL) was modified suggesting that foci might have an altered metabolism as often observed during cancer progression." (PMID 32218467, 2020).
cardiac disease (1 paper, 2022). "However, the role of ETNPPL in cardiac disease has not been reported." (PMID 35433888, 2022).
cardiovascular disease (1 paper, 2022). "However, the specific function of ETNPPL remains unclear currently, especially in the study of cardiovascular disease." (PMID 36295481, 2022).
neurological disorders (1 paper, 2024). "Moreover, an association was found between neurological disorders and altered gene expression of ETNPPL, which decreased by 72% in the prefrontal cortex of post-mortem depressed patients." (PMID 39684817, 2024).
ETNPPL also shares sentences with these, for which no sentence is quoted: hepatocellular carcinoma (3 papers); psychiatric diseases (2); schizophrenia (2); bipolar disorder (1); chronic kidney disease (1); clear cell renal cell carcinoma (1); colorectal cancer (1); depression (1); dilated cardiomyopathy (1); heart failure (1); idiopathic interstitial pneumonia (1); immune system disease (1); liver fibrosis (1); mood disorder (1); nephrotic syndrome (1); pancreatic cancer (1); Parkinson disease (1); psoriasis (1); squamous cell carcinoma (1); tuberculosis (1).